H1-5 (H1.5 linker histone, cluster member)
Description:
Histone H1 protein binds to linker DNA between nucleosomes forming the macromolecular structure known as the chromatin fiber (By similarity). Histones H1 are necessary for the condensation of nucleosome chains into higher-order structured fibers and promote formation of the H3K27me3 mark by the PRC2/EED-EZH2 complex. Also acts as a regulator of individual gene transcription through chromatin remodeling, nucleosome spacing and DNA methylation (By similarity).
Synonyms: H1F5; HIST1H1B; H1b; H1s-3; H1; H1.5
Tractability: PROTAC: ubiquitination databases record sites on it.
Gene: Protein-coding gene on chromosome 6 (27,866,792 to 27,867,588, reverse strand). Ensembl gene ENSG00000184357.
Subcellular location: Nucleus; Chromosome
Subcellular location (Human Protein Atlas): Nucleoplasm
Pathways (Reactome):
Cellular responses to stimuli: Formation of Senescence-Associated Heterochromatin Foci (SAHF)
Programmed Cell Death: Apoptosis induced DNA fragmentation
Gene Ontology:
Molecular function: chromatin DNA binding; histone deacetylase binding; protein binding; RNA binding; double-stranded DNA binding; nucleosomal DNA binding; DNA binding; structural constituent of chromatin
Biological process: chromatin organization; establishment of protein localization to chromatin; negative regulation of transcription by RNA polymerase II; protein stabilization; chromosome condensation; negative regulation of DNA recombination; nucleosome assembly
Cellular component: chromatin; chromosome; heterochromatin; nucleoplasm; nucleus; euchromatin; nucleosome
Genetic constraint (gnomAD): Loss-of-function variants: 6 observed, 6.64 expected, observed/expected ratio (o/e) 0.9, 90% interval 0.49 to 1.69. That is too few expected variants to judge how well the gene tolerates losing a copy. Missense variants: 521 observed, 307.82 expected, observed/expected ratio (o/e) 1.69, 90% interval 1.58 to 1.82. Synonymous variants: 250 observed, 132.18 expected, observed/expected ratio (o/e) 1.89, 90% interval 1.69 to 1.98.
Homologues: Orthologues: chimpanzee H1-5 (99% identical), macaque H1-5 (99% identical), dog H1-5 (94% identical), mouse H1f5 (91% identical), rat H1f5 (88% identical), zebrafish si:ch73-368j24.12 (63% identical), Caenorhabditis elegans hil-3 (26% identical), Caenorhabditis elegans hil-6 (24% identical), Caenorhabditis elegans hil-2 (24% identical), Caenorhabditis elegans hil-4 (23% identical), Caenorhabditis elegans hil-5 (23% identical). Paralogues in human: H1-4 (85% identical), H1-3 (79% identical), H1-2 (77% identical), H1-1 (67% identical), H1-6 (49% identical), H1-0 (40% identical), H1-8 (33% identical), H1-10 (28% identical), H1-7 (25% identical).
Diseases named in the same sentence as H1-5 in open-access papers:
H1-5 is named in the same sentence as 28 diseases in open-access papers, as found by Europe PMC text mining. Sharing a sentence is not in itself a finding about the gene and the disease. The quoted sentences say what the papers report.
tumor (5 papers, 2018 to 2024). "Our study found seven downstream factors that may be associated with chemoresistance, LTF, SOD2, STAT1, CDKN2A, CD81, RAC1, and NDRG1 and five factors that may be associated with tumor development, CCN1, DCTN3, MUC1, H1-5, and SLC1A5." (PMID 35421932, 2022).
H1-5 also shares sentences with these, for which no sentence is quoted: cancer (7 papers); breast carcinoma (5); COVID-19 (3); glioma (3); prostate carcinoma (3); lymphoma (2); melanoma (2); Alzheimer disease (1); bipolar disorder (1); breast tumor (1); colon cancer (1); endometrial cancer (1); gingivitis (1); glioblastoma (1); hepatoma (1); HIV-1 infection (1); leiomyoma (1); leiomyosarcoma (1); leukemia (1); mucositis (1); neurological diseases (1); osteosarcoma (1); prostate adenocarcinoma (1); pulmonary neuroendocrine tumors (1); renal fibrosis (1); thyroid cancer (1); viral hepatitis (1).